CCL2 (C-C motif chemokine ligand 2)
Diseases named in the same sentence as CCL2 in open-access papers (continued):
Sharing a sentence is not in itself a finding about the gene and the disease.
viral infection (185 papers, 2007 to 2026). "CCL2 is associated with infiltration of inflammatory monocytes into the brain during acute viral infection." (PMID 39817772, 2025). "Our results show that viral infection of mice caused mild disease and induced the depletion of CCL2 in the periphery." (PMID 36365071, 2022). "Several studies demonstrated earlier that the expression of chemokines, such as Ccl2, Ccl3, Ccl4, Ccl5, and Cxcl10, during viral infection is associated with enhanced trafficking of leukocytes into the brain." (PMID 34379515, 2021). "As expected, pro-inflammatory genes (e.g., Ifnb1, MCP-1/Ccl2, Cxcl10) associated with a response to viral infection were most prominently upregulated in H3N2 and H5N1 infected mice, as evident in gene ontology (GO) analyses." (PMID 32231671, 2020). "In this context, gene expression signatures in the lungs of SARS-CoV-2-infected patients who succumb to viral infection showed high expression of MCP-1/CCL2 and IP-10/CXCL10, which was linked to type I and II IFN responses." (PMID 33257679, 2020). "CCL2 has been linked to infiltration of monocytes and leukocytes into the brain during virus infection." (PMID 31664929, 2019). "Interestingly, according to GO terms, a majority of these downregulated genes is associated with the host pro-inflammatory response to viral infection (e.g., Ccl2, IL-6, IL-1β)." (PMID 32231671, 2020). "Previous studies have indicated that inflammatory chemokines, such as CCL2, significantly impact the immune response to viral infections by increasing the cytotoxicity of the inflammatory immune cells and promoting the release of antiviral mediators." (PMID 38816794, 2024). "Nevertheless, expression of IL-6, TNF-α, and CCL-2 in the lung and brain increased with viral infection." (PMID 39077737, 2024). "CCL2 is an essential mediator of inflammation that is essential for the management of viral infections." (PMID 38803488, 2024). "Virus infection typically results in an upregulation of chemokines (CCL2 and CCL5) and alterations in tight junction protein expression, thereby modifying endothelial cell function and increasing vascular permeability." (PMID 39021576, 2024). "Viral infection induces a variety of proinflammatory cytokines and chemokines including IL-1b, IL-6, TNFa, CCL2, CCL3, CXCL1, CXCL2, CXCL9 and CXCL1034,35." (PMID 38750107, 2024). "In response to inflammatory stimuli such as cytokines and bacterial or viral infections, a range of cell types, including macrophages, endothelial cells, and fibroblasts, generate CCL2." (PMID 37667317, 2023). "Since cytokine and chemokine release modulates responses to bacterial and viral infection, we evaluated the induction of selected interleukin/chemokines, IL-6, IL-8, IFNα and CCL2 mRNA expression following treatment of hfBECs with PAMPS." (PMID 36721242, 2023). "High levels of CCL2 can assist viral infection by recruiting target cells to affected sites and increasing the expression of CXCR4 (a co-receptor for HIV)." (PMID 37999614, 2023). "Viral infection dramatically increased the expression of IL-6 and CCL2 in the lungs, while VV116, nirmatrelvir, and combination treatments resulted in a reduction in these cytokines during the initial days." (PMID 37735468, 2023). "It has been demonstrated that the reduction of CCL2 levels was beneficial in the treatment of individuals with HIV, while high levels were associated with immunological failure in the viral infection." (PMID 37999614, 2023). "Further, the level of CCL2 is also regulated by viral infection, such as severe acute respiratory syndrome coronavirus and human cytomegalovirus." (PMID 37766274, 2023). "In general, CCL2 expression is activated after viral infection and recruits Langerhans and DCs, respectively." (PMID 36188003, 2022). "Both CXCL10 and CCL2 are important chemokines involved in the infiltration of leukocytes into the CNS after virus infection." (PMID 35215199, 2022).
viral infection (continued). "N2a cells also upregulated CCL2 expression in response to virus infection, but the expression was lower and later than that in C8-D1A cells." (PMID 35529855, 2022). "CCL2 is already known to have a role in the neuro-inflammatory response in the nervous system, acting as a pro-inflammatory chemokine during different viral infections." (PMID 35215144, 2022). "MCP-1 (also termed CCL2) has a positive effect on the chemotaxis of monocytes/macrophages and neutrophils and, thus, was activated in a bacterial or viral infection." (PMID 36296170, 2022). "During the early stage of viral infection, cytokines (IL-1, IL-2, IL-8, IL-10, CCL2, CCL7, IFN-α, IFN-β, and TNF-α) have essential functions in the recruitment of immune cells, defense against the infection, and promotion of inflammation." (PMID 34603560, 2021). "Given that the epithelium influences leukocyte recruitment during viral infection through chemokine signaling, we evaluated the expression of Ccl2, Ccl3, and Ccl4 in lung homogenates from PBS-treated and RSV-infected mice." (PMID 33187989, 2021). "Viral infection triggers the migration of circulating monocytes to the lung guided by pro-inflammatory cytokines, such as CCL2 and CCL3, increasing the number of defending mononuclear phagocytes and enhancing inflammation." (PMID 34367190, 2021). "Since then the field has expanded rapidly to show that type I IFNs decrease neutrophil chemoattractants (CXCL1/2), reduce IL-17 producing γδ T cells, and impair CCL2- mediated recruitment of macrophages following viral infection." (PMID 32265937, 2020). "In total 20 ISGs were significantly upregulated in the RSV-infected mice compared to the non-infected mice and some of the top 10 upregulated genes, such as Irf7,Cxcl10, Ccl2, and Ccl4, are all ISGs known to be induced in response to viral infections." (PMID 33363532, 2020). "Since cytokine and chemokine release is the primary systemic response after bacterial or viral infection, we evaluated the LPS and ssRNA inflammatory responses by examining the induction of IL-6, IL-8, and CCL2." (PMID 31561453, 2019). "In mild persistent asthmatics, viral infection was associated with increased protein abundance of CXCL10, sICAM-1, CCL2, CCL4, CCL5, CCL20 and CCL24." (PMID 30463560, 2018). "In moderate-to-severe persistent asthmatics, viral infection was associated with increased protein abundance of CXCL10, IL-4, sICAM-1, CCL2, CCL20 and CCL24." (PMID 30463560, 2018). "This regulation is mediated by CCL2, a β-chemokine which is produced predominantly by astrocytes upon viral infection." (PMID 28425451, 2017). "We observed increased level of inflammatory mediators (IL-1α, IL-1β, IL-6, MIP-1α (CCL3), MIP-1β (CCL4), RANTES (CCL5), MCP-1 (CCL2)) following H5N3 virus infection at 4, 8 and 20 hpi compared to cells infected with the H1N1/WSN, H5N2 and H9N2 viruses." (PMID 28558796, 2017). "Elevated numbers of mo-DCs that express CCR2 (chemokine receptor for CCL2) or produce high amounts of TNF-α and NO are associated with greater morbidity and mortality in response to viral infection." (PMID 26965109, 2016). "Inflammatory mediators MCP1 (CCL2), RANTES (CCL5) and IP-10 were found to be elevated in alcoholism, which has been reported previously in association with alcoholism-related viral infection, alcoholic liver and pulmonary disease." (PMID 27043532, 2016). "We next measured levels of immunomodulatory mediators in lung homogenates and report that viral infection in fibrotic lungs (Bleo+MHV-68) led to a significant increase in lung levels of CCL2, IL-1β, TNFα and IL-10 above the levels detected for Bleo lungs." (PMID 26138704, 2015). "CCL2 codes for a chemokine expressed in neurons, microglia, and astrocytes that is induced by viral infection, head trauma, and cytokines." (PMID 25905630, 2015).
viral infection (continued). "The serum concentrations of the CXCL9 and CCL2 chemokines appear to be unaffected by pregnancy and tend to be poorly induced by influenza-like or H1N1pdm2009 viral infection." (PMID 25254368, 2014). "Similar to MARC-145 cells, the virus infection resulted in increased expression of IL-1β, IL-8, IL-10, CCL2 and CXCL10 in PAMs." (PMID 23637938, 2013). "Our results indicated that the release of CCL2 and IL-10 from DCs was positively related to viral infection while the production of IFN-α and TNF-α was negatively related to viral replication." (PMID 21269456, 2011). "Indeed, previous studies have demonstrated that the NF‐κB signalling pathway is activated during oxidative stress and viral infection, which induces the expression of CCL2." (PMID 40500868, 2025). "For example, exopolysaccharides of Streptococcus thermophilus ST538 induced the expression of IL6 and CCL2 in porcine intestinal epitheliocytes which could aid against a virus infections." (PMID 39712028, 2024). "Additionally, upregulated expression of antiviral genes such as GBP1, GBP2 and CCL2 was also observed, which is closely related to the inflammatory response elicited by viral infection." (PMID 39872814, 2024). "Furthermore, viral infection increased the mRNA expression of cytokines (Il6, Tnf), chemokines (Cxcl10, Ccl2), and interferon-responsive genes (Ifnb1, Ifit3, Irf7, Gbp5 and Isg15)." (PMID 37081549, 2023). "Administration of bindarit during chronic virus infection offered an additional approach to inquire whether CCL2 functions are required to maintain NCI." (PMID 37085605, 2023). "CCL2 is a well-known CC chemokine, which is not only one of the critical chemokines in regulating monocytes/macrophage migration and infiltration, but also plays a role in cancer, autoimmune diseases, bacterial and viral infections, and many kidney diseases." (PMID 36793712, 2023). "Except for ccl2, which was consistently lower at all time point tested in rhMPV- ΔG virus-infected mice, all other chemokines were detected at higher concentrations at day 7 post-inoculation in rhMPV -ΔG virus infection." (PMID 35958551, 2022). "On the other hand, virus infections trigger the production of inflammatory cytokines and chemokines in the respiratory tract including interleukin (IL)-6, chemokine (C-C motif) ligand 2 (CCL2), CCL5, CCL8, chemokine (C-X-C motif) ligand 8 (CXCL8), CXCL9, CXCL16, and CXCL2." (PMID 34578229, 2021). "CCL2 could be released by multiple organs and could contribute to the inflammatory process during viral infection." (PMID 34220524, 2021). "Interestingly, MSC are usually resistant to viral infection due to their expression of ISGs such as IFITM, IFI6, ISG15, SAT1, PMAIP1, p21/CDKN1A, and CCL2 that preempt viral infection." (PMID 33808241, 2021). "Virus infection leads to a modest increase in secretion of CCL2, IL-6, IL-8, and GM-CSF." (PMID 29228979, 2017). "In pulmonary inflammation caused by viral infection, the loss of RIPK3 reduces the secretion of various inflammatory cytokines and chemokines, especially CXCL10 (also known as interferon-γ-inducible protein 10 [IP-10]) and chemokine ligand 2 (CCL2; monocyte chemoattractant protein 1 [MCP-1])." (PMID 38684668, 2024). "In this context, it has been shown that HIV-derived Tat and gp120 proteins increase the expression and release of CCL2, which may facilitate the viral infection by upregulating the expression of CXCR4 (a co-receptor for HIV) and the recruitment of target cells to infection sites." (PMID 37999614, 2023). "Interestingly, MSC are usually resistant to viral infection due to their expression of interferon (IFN) stimulated genes (ISG) such as IFITM (interferon-induced transmembrane family), IFI6, ISG15, SAT1, PMAIP1, p21/CDKN1A, and CCL2 that preempt viral infection." (PMID 32766251, 2020).
viral infection (continued). "Therefore, to mechanistically delineate the contribution of macrophages to CCL2 production during viral infection, monocyte-derived macrophages were stimulated with purified viral PAMPS, poly I:C, a TLR3 agonist, and ssRNA40, which is derived from the HIV-1 long terminal repeat and activates TLR7/8." (PMID 29466439, 2018). "Cytokines and inflammatory chemokines (IL-1ra, IL-6, TNF-α, IL-8, G-CSF, MCP-1/CCL2, and PDGF) have been shown to be elevated in the CSF samples of pediatric patients in whom viral infection led to the SIDS in comparison with the control groups." (PMID 38675861, 2024). "We found that virus-induced mRNA levels of key proinflammatory cytokines, IL6, IL1B, CCL2, and CXCL10, were decreased in monocytic cell lines, namely THP1 and U937, and in PBMCs treated with Senexin B prior to viral infection." (PMID 37376593, 2023). "CCL2 and CXCL10 play proinflammatory roles in viral infections by stimulating the activation and migration of immune cells to the sites of viral replication including the brain." (PMID 36890518, 2023). "The results showed that phillyrin treatment alleviated pneumonia induced by virus infection and significantly ameliorated the upregulation of multiple pro-inflammatory cytokines and chemokines (e.g., IL-1β, CXCL1, CCL3, CCL2, CCL5 and so on) in BALF." (PMID 37957672, 2023). "Real-time quantitative PCR (qRT-PCR) verified that the chemokine CCL2, CCL3, and CCL5 expression levels gradually increased with prolonged viral infection (MOI, 0.5), with the increase in CCL5 expression the most obvious." (PMID 36317881, 2022). "Similar findings were observed in animal experiments, where chemokines increased in 3 days after viral infection, and levels of chemokines such as CCL8 and CCL2 continued to expand after 7 days despite a decrease in viral load." (PMID 35747501, 2022). "It is relevant to consider that MSC are usually resistant to viral infection due to their expression of interferon (IFN), and, subsequently, IFN-stimulated genes (ISGs) (such as IFI6, ISG15, SAT1, PMAIP1, p21/CDKN1A, and CCL2)." (PMID 33808241, 2021). "CCR2, the receptor of CCL2 has been reported to play a critical role in the recruitment of DCs and CD8+ T cells during viral infections." (PMID 34194439, 2021). "Upon viral infection, AMs produce high levels of cellular mediators, including IL-1β, CCL3, CCL7 and CCL2, also known as monocyte chemotactic protein 1 (MCP1), which rapidly recruits CCR2-expressing bone marrow-derived monocytes into the lung." (PMID 34367190, 2021). "Increased levels of CCL2 and CXCL1 have also been reported in neutrophil- and monocytes-infiltrated tissues in different viral infections." (PMID 33858301, 2021). "First, Type II alveolar cells will secrete a host of inflammatory cytokines in response to viral infection such as IL-1β, IL-6, TNF-α, CXCL10, and CCL2 that will act to recruit other inflammatory cells to help abate the viral infection." (PMID 32760409, 2020). "Several chemokines were also involved in response to viral infection (CCL4, CCL11, CXCL10), bacterial infection (CCL2, CCL3, CXCL10), as well as to toxic substances insults (CCL3, CCL4)." (PMID 32295518, 2020). "Previous studies have implicated activated microglia in leukocyte recruitment into the brain upon virus infection, and showed that antibodies to CXCL10 and CCL2 (MCP-1) reduce the migration of murine splenocytes toward HSV-infected microglia in vitro." (PMID 30027450, 2018). "At day 2 postinfection, both TNF-α and IL-6 transcripts were moderately induced by wild-type virus, while CCL2, CCL4, CXCL9, and CXCL10 mRNA levels were all highly elevated by wild-type virus infection." (PMID 29138302, 2017). "The levels of either gene expression or cytokine proteins (IL-1α, TNFα, IL-6, CXCL10, CCL5, CCL2, CCL3, CCL4, and CCL5) in RSV-infected PMФ are comparable to the H5N3 virus infection." (PMID 28558796, 2017).
viral infection (continued). "Activated endothelium can also secrete proinflammatory cytokines and chemokines such as IL-6, MIG/CXCL9, IP-10/CXCL10, type I and type II IFNs, MCP-1/CCL2, and TNF-α in response to a virus infection." (PMID 26965109, 2016). "Thus, since the heterosexual route through female reproductive tract mucosal surfaces is the predominant mode of HIV-1 transmission, targeting CCL2 may offer a tantalizing possibility of leveraging innate immunity to fend off viral infection at the entry route." (PMID 25608886, 2015). "A curious observation was the inverse correlation of the expression levels of the transcripts of IL-6, TNF-α, CXCL9, CCL2 and CCL3 and the virus infection dose." (PMID 24086645, 2013). "We also found viral exacerbation to correlate with inhibition of neutrophil and NK cell recruitment early in the viral infection, as well as reduction in the levels of the chemokines KC (CXCL1) and MCP-1 (CCL2), which are chemoattractants for these cells." (PMID 21533103, 2011). "However, in the serum of SARS-CoV-2–infected macaques, we found a transient virus infection–related increase in 2 interferon-γ–driven inflammatory cytokines, CXCL10 and CXCL11, and an increase of CCL2, whereas interleukin-6 was elevated in only 1 animal." (PMID 40876955, 2026). "Importantly, CCL2 and CCL5 are known to drive inflammatory monocyte infiltration into the brain during viral infection, supporting a key role of these chemokines on inflammation." (PMID 41139159, 2025). "Some markers of early virus-induced inflammation were not altered and we detected similar levels of IL1α, IFNβ or CCL2 in all mice one day after virus infection as a potential result of pattern-recognition receptor activation in infected cells." (PMID 39472590, 2024). "To explore the effect of SPJ treatment on cytokine expression, we used real‐time PCR and observed that viral infection led to increased expression of cytokines and chemokines, including IL‐6, IL‐1β, TNF‐α, IL‐10, IFN‐α, IFN‐β, and IFN‐γ, as well as CXCL‐2, CXCL‐10, CCL‐2, CCL‐3, and CCL‐5." (PMID 37544014, 2023). "Previous findings suggest that this receptor homologue may be involved in host immune response modulation by the downregulation of monocyte chemoattractant protein I (MCP-1; CCL2), which is required for immune cell recruitment to sites of viral infection." (PMID 36839451, 2023). "Even though CLEC2.Fc was unable to inhibit virus infection and replication, CLEC2.Fc inhibited the expression of IL‐6, CXCL2, CXCL5, CCL2, and IP‐10 at day 3 and day 5 post‐infection, and the expression of TNF‐α, IFN‐γ, IL‐10, and CXCL1 was also suppressed at day 5 post‐infection (red columns)." (PMID 37211986, 2023). "CCL2, CCL3, CCL4, and CCXL10 are produced in the lung in the early phase of lung inflammation, working as a chemotactic factor for macrophages, NK cells, and T cells during viral infection." (PMID 34851149, 2022). "Upregulated expression of cytokines, chemokines and growth factors was commonly observed in patients and animals with lymphopenia induced by viral infection, including IL-2, IL-6, IL-12, IL-18, IL-1β, IFN-γ, CCL2/MCP-1, CXCL1, CXCL8/IL-8, CCL3/MIP-1-α, CCL7/MCP-3, CXCL10/IP-10 and CXCL9/MIG." (PMID 34578457, 2021). "Finally, dSpace analysis identified several genes (CCL2, OASL, CASP7, TMEM123, MAFB, VRK2, UBE2L6, NAPA) higher in patients with mild viral infection than those with severe viral infection or HCs." (PMID 33765435, 2021). "CCL2, a type I IFN receptor-mediated chemoattractant that promotes monocyte migration to the site of infection, and OASL, a type I IFN-induced gene, had higher expression in patients with mild viral infection." (PMID 33765435, 2021). "In mock‐treated organoids, most of the cells are negative for CCL2 signal, while expression is induced upon viral infection especially at 4 hpi." (PMID 34309190, 2021).